CIAO3 (cytosolic iron-sulfur assembly component 3)
Description:
Component of the cytosolic iron-sulfur protein assembly (CIA) complex, a multiprotein complex that mediates the incorporation of iron-sulfur cluster into extramitochondrial Fe/S proteins. Seems to negatively regulate the level of HIF1A expression, although this effect could be indirect.
Synonyms: IOP1; NARFL; PRN; FLJ21988; HPRN; NAR1; LET1L
Tractability: Antibody: the Human Protein Atlas places it where antibodies can reach. PROTAC: ubiquitination databases record sites on it.
Gene: Protein-coding gene on chromosome 16 (729,759 to 741,329, reverse strand). Ensembl gene ENSG00000103245.
Subcellular location (Human Protein Atlas): Cytosol; Plasma membrane
Pathways (Reactome):
Metabolism: Cytosolic iron-sulfur cluster assembly
Gene Ontology:
Molecular function: protein binding
Biological process: intracellular oxygen homeostasis; iron-sulfur cluster assembly; regulation of gene expression; response to hypoxia
Cellular component: cytosolic [4Fe-4S] assembly targeting complex; cytoplasm
Genetic constraint (gnomAD): Loss-of-function variants: 45 observed, 50.6 expected, observed/expected ratio (o/e) 0.89, 90% interval 0.7 to 1.14. The upper end of that interval is the gene's LOEUF score, 1.14, which puts it in group 4 of 6, group 1 being the genes least tolerant of losing a copy. Missense variants: 668 observed, 619.27 expected, observed/expected ratio (o/e) 1.08, 90% interval 1.01 to 1.15. Synonymous variants: 314 observed, 261.34 expected, observed/expected ratio (o/e) 1.2, 90% interval 1.1 to 1.32.
Homologues: Orthologues: chimpanzee CIAO3 (99% identical), macaque CIAO3 (98% identical), mouse Ciao3 (88% identical), guinea pig CIAO3 (86% identical), rat Ciao3 (83% identical), dog CIAO3 (80% identical), tropical clawed frog ciao3 (72% identical), pig CIAO3 (68% identical), zebrafish narfl (68% identical). Paralogues in human: NARF (46% identical), NDUFS1 (17% identical).
Diseases named in the same sentence as CIAO3 in open-access papers:
CIAO3 is named in the same sentence as 14 diseases in open-access papers, as found by Europe PMC text mining. Sharing a sentence is not in itself a finding about the gene and the disease. The quoted sentences say what the papers report.
cervical squamous cell carcinoma (1 paper, 2023). A squamous cell carcinoma arising from the cervical epithelium. "It contained 11 prognostic genes of M33 in cervical squamous cell carcinoma (CESC), including the cell-cycle repressor E4F1 and the cytosolic iron–sulfur protein assembly component CIAO3 (previously known as NARFL)." (PMID 37907329, 2023).
CIAO3 also shares sentences with these, for which no sentence is quoted: adenocarcinoma (1 paper); breast carcinoma (1); cancer (1); epilepsy (1); infection (1); lung carcinoma (1); neurodegenerative disease (1); non-small cell lung carcinoma (1); pertussis (1); Pulmonary arteriovenous malformation (1); pulmonary hypertension (1); squamous cell carcinoma (1); tumor (1).